SELE (selectin E)
Description:
Cell-surface glycoprotein having a role in immunoadhesion. Mediates in the adhesion of blood neutrophils in cytokine-activated endothelium through interaction with SELPLG/PSGL1. May have a role in capillary morphogenesis.
Synonyms: LECAM2; CD62E; ELAM1; ESEL; ELAM; selectin-e
Tractability: Small molecule: a drug acting on it is in phase 2 or 3 trials; a structure with a bound ligand is known; a high-quality ligand is known; it belongs to a druggable protein family. Antibody: a drug acting on it is in phase 1 trials; UniProt places it where antibodies can reach, with high confidence; its Gene Ontology location is reachable by antibodies, with high confidence; UniProt predicts a signal peptide or a membrane-spanning region. PROTAC: ubiquitination databases record sites on it; a small molecule that binds it is known.
Target class: Adhesion
Gene: Protein-coding gene on chromosome 1 (169,722,640 to 169,764,705, reverse strand). Ensembl gene ENSG00000007908.
Subcellular location: Cell membrane
Pathways (Reactome):
Hemostasis: Cell surface interactions at the vascular wall
Gene Ontology:
Molecular function: oligosaccharide binding; phospholipase binding; protein binding; sialic acid binding; transmembrane signaling receptor activity
Biological process: actin filament-based process; heterophilic cell-cell adhesion; leukocyte cell-cell adhesion; leukocyte tethering or rolling; phospholipase C-activating G protein-coupled receptor signaling pathway; positive regulation of receptor internalization; response to interleukin-1; calcium-mediated signaling; inflammatory response; leukocyte migration involved in inflammatory response; positive regulation of leukocyte tethering or rolling; regulation of inflammatory response; response to cytokine; response to lipopolysaccharide; response to tumor necrosis factor; cell adhesion
Cellular component: caveola; clathrin-coated pit; cortical cytoskeleton; extracellular region; membrane raft; perinuclear region of cytoplasm; plasma membrane; external side of plasma membrane; membrane
Genetic constraint (gnomAD): Loss-of-function variants: 50 observed, 73.55 expected, observed/expected ratio (o/e) 0.68, 90% interval 0.54 to 0.86. The upper end of that interval is the gene's LOEUF score, 0.86, which puts it in group 3 of 6, group 1 being the genes least tolerant of losing a copy. Missense variants: 740 observed, 751.89 expected, observed/expected ratio (o/e) 0.98, 90% interval 0.93 to 1.05. Synonymous variants: 279 observed, 267.5 expected, observed/expected ratio (o/e) 1.04, 90% interval 0.94 to 1.15.
Homologues: Orthologues: chimpanzee SELE (98% identical), macaque SELE (96% identical), dog SELE (79% identical), rat Sele (74% identical), mouse Sele (73% identical), rabbit SELE (67% identical), guinea pig SELE (66% identical), zebrafish selp (37% identical), tropical clawed frog SELE (27% identical). Paralogues in human: SELP (46% identical), SELL (26% identical), CSMD2 (24% identical), CSMD3 (24% identical), CSMD1 (23% identical), SVEP1 (21% identical), CR2 (19% identical), CR1 (17% identical), CFH (15% identical), C4BPA (14% identical), SEZ6L2 (14% identical), PAPPA (13% identical), and 27 more.
Diseases named in the same sentence as SELE in open-access papers:
SELE is named in the same sentence as 354 diseases in open-access papers, as found by Europe PMC text mining. Sharing a sentence is not in itself a finding about the gene and the disease. The quoted sentences say what the papers report.
endothelial dysfunction (179 papers, 2005 to 2026). In vascular diseases, endothelial dysfunction is a systemic pathological state of the endothelium (the inner lining of blood vessels) and can be broadly defined as an imbalance between vasodilating and vasoconstricting substances produced by (or acting on) the endothelium. "Levels of SELE and other cellular adhesion molecules have previously been associated with DM, increasing HbA1c levels, blood pressure and microalbuminuria, all reflecting (early) endothelial dysfunction." (PMID 34372849, 2021). "Not surprisingly, many of the most upregulated genes are well-known markers of endothelial dysfunction (e.g., SELE, ICAM1, SOD2, IL8, IL1B)." (PMID 31287004, 2019). "While IL-1β has been well established to promote atherosclerosis, END1 and SELE are markers for endothelial dysfunction and may also contribute to the development of CVD." (PMID 39253968, 2024). "It has been widely suggested that the soluble form of E-selectin also known as SELE, which is released during inflammation, is a biomarker of endothelial dysfunction during COVID-19 disease." (PMID 36949176, 2023). "This immune activation leads to endothelial dysfunction through multiple convergent pathways: direct cytokine‐mediated endothelial activation (increased ICAM‐1, VCAM‐1, E‐selectin expression), anti‐tTG antibody cross‐reactivity with cerebral endothelium, and systemic inflammatory effects." (PMID 40114993, 2025). "This could be indicative of endothelial dysfunction and/or other mediators influencing VCAM-1 and E-selectin expression." (PMID 32934781, 2020).
atherosclerosis (176 papers, 2007 to 2025). A disease characterized by the build-up of fatty material and calcium deposition in the arterial wall resulting in partial or complete occlusion of the arterial lumen. "The SELE gene also appears to be associated with atherosclerosis, with monocytes adhering to vascular endothelial cells and migrating into the endothelium to take up lipids and transform into foam cells as an early event in the formation of atherosclerosis." (PMID 35194526, 2022). "This transcriptome enriches key AD pathways more than the individual studies, and associates AD with novel pathways, such as atherosclerosis signaling (IL-37, selectin E/SELE)." (PMID 26459294, 2015). "Our transcriptome is the first association of AD genomic fingerprinting with the atherosclerosis signaling pathway, which includes genes associated with vascular inflammation (SELE, IL-37, S100A8)." (PMID 26459294, 2015). "Another polymorphism of the SELE gene, the G98T mutation, was previously reported to be associated with a higher risk for early severe atherosclerosis in 99 cases and 100 controls in German Caucasians." (PMID 24260191, 2013). "Several polymorphisms in the SELE gene, such as A561C, G98T, L554F, G2692A and C1091T, were successively reported to be associated with atherosclerosis and CAD." (PMID 24260191, 2013). "SELE is explicitly expressed from endothelial cell origin, with evidence suggesting its role in the leukocyte adhesion process to endothelial surfaces in response to inflammation and is strongly implicated in atherosclerosis pathogenesis." (PMID 39408698, 2024). "Currently, the SELE gene is reported as a high-risk factor involved in atherosclerosis development." (PMID 35768776, 2022). "Here, we present data indicating that many atherosclerosis and cardiovascular risk-related proteins that were found to be up-regulated in other Olink studies (e.g., SELE/E-selectin, TNFSF14/LIGHT, VEGFA, RETN/resistin, MMPs) are in fact suppressed by dupilumab in tape-stripped skin lesions." (PMID 32849633, 2020). "E-selectin expression was significantly enhanced at sites predisposed to atherosclerosis." (PMID 29126223, 2018). "The relative upregulation of inflammatory processes in the transcriptomics data can most likely be attributed to genes encoding pro-inflammatory proteins such as VCAM1, ICAM1, and SELE, which are shown to be elevated in the initial stages of atherosclerosis." (PMID 39695567, 2024). "The SELE gene is expressed in cytokine-stimulated endothelial cells and appears to participate in the pathogenesis of atherosclerosis." (PMID 34671380, 2021). "Proteins related to atherosclerosis/cardiovascular risk (e.g., SELE/E-selectin, IGFBP7, CHIT1/ chitotriosidase-1, AXL) also significantly decreased after treatment." (PMID 32849633, 2020). "Endothelial activation, resulting in E-selectin expansion, induces leukocyte rolling along the vascular wall and mediates inflammation in various diseases, including atherosclerosis." (PMID 32942670, 2020). "E-selectin’s importance to atherosclerosis was demonstrated in studies showing increased E-selectin on arterial plaque surfaces and reduced development of atherosclerotic lesions in mice lacking SELE." (PMID 28323859, 2017). "This is the first report that 15-oxo-ETE promotes early pathological process of atherosclerosis by accelerating E-selectin expression and monocyte adhesion." (PMID 28701173, 2017). "15-oxoETE promotes E-selectin expression and PKC-dependent monocyte adhesion, which indicating that 15-oxoETE is probably a potential risk factor of atherosclerosis." (PMID 28701173, 2017). "Specifically, SELE, the most upregulated gene, is a glycoprotein actively involved in the first steps of atherosclerosis since it sustains the leukocytes adhesion to endothelial wall and their passage to the subendothelial space." (PMID 28224128, 2017).
atherosclerosis (continued). "Although the in vivo study has suggested that E-selectin and P-selectin exert similar effects of leukocyte adhesion on atherosclerosis lesions." (PMID 24498435, 2014). "E-selectin, the product of the SELE gene, is closely associated with hypertension, coronary heart diseases and atherosclerosis, and thus appears to be a risk factor for these conditions." (PMID 20796317, 2010). "This is supported by upregulation of SELE, ICAM4, and SLAMF4 with involvement in leukocyte activation, adhesion, and general immune regulation and positive regulation of MAPK signalling, all of which have been implicated in atherosclerosis pathophysiology." (PMID 39408698, 2024). "Since P2 × 7 stimulation has been described as promoter of E‐selectin expression in atherosclerosis, we investigated further whether P2 × 7 regulates the expression of E‐selectin in the pulmonary microcirculation upon aQD triggered inflammation." (PMID 39364760, 2024). "Notably, many of the misexpressed genes were well-known atherosclerosis-related genes, including SELE, which is highly expressed in atherosclerosis patients." (PMID 30187887, 2018). "Interestingly, Atherosclerosis Signaling was the second highest IPA pathway, and includes genes previously associated with vascular inflammation, such as IL-37, SERPINA1, S100A8, selectin E/SELE, lipoprotein lipase/LPL, and MMP1/3/9." (PMID 26459294, 2015). "In early atherosclerosis, also endothelial P-selectin expression is crucial in the progression of the atherosclerotic lesion, and therefore this close link between endothelial activation (and E-selectin expression) and sP-selectin was expected." (PMID 19578494, 2008). "The common mechanisms shared in both are linked with atherosclerosis signaling and inflammatory response with at least the following target genes: Tnfrsf12a, Pla2g2f, Il1f9, Col1a1, Col1a2, and Col3a1 in brain, while Tnfrsf12a, SELP, SELE, IL6, and IL1A in myocardium." (PMID 29681850, 2018). "It downregulates E-selectin expression and decreases NLPR3 inflammasome activation, suppressing IL-1β and IL-6 release, which are critical inflammatory mechanisms in atherosclerosis." (PMID 39113913, 2024). "Ten key regulated genes (including Pla2g2f, Il1f9, Col1a1, Col1a2, and Col3a1 in the brain, while SELP, SELE, IL6, and IL1A in the myocardium, and Tnfrsf12a in both) are correlative with atherosclerosis signaling and inflammatory response." (PMID 29681850, 2018). "Selectin-E showed negative correlation, as its activity is more pronounced in earlier stages of atherosclerosis than in later phases." (PMID 40821632, 2025). "Notably, these correlations might suggest a link between the metabolome and protein markers related to immune signalling (LTα, CD6, CCL21, SELE), energy balance and metabolism-related hormones (IGFBP1, SHGB, ADM, leptin, and STC1), and atherosclerosis/thrombosis inhibitor (PAI1)." (PMID 39154540, 2024).
diabetes (73 papers, 2007 to 2026). "The top 5 proteins we identified (GDF15, GAL4, IL1RT1, CTSD and SELE) are robustly associated with diabetes in a variety of studies, consistent with our findings." (PMID 34372849, 2021). "Furthermore, the present result from Iraqi patients aligns with previous studies about Iraqi patients with other diseases (e.g., type 2 diabetes mellitus) that showed a positive association with SELE polymorphisms, and these local studies all concluded that SELE could be a risk factor." (PMID 36617649, 2022). "Other Iraqi studies have emphasized that heterozygous genotypes in different SNPs of the SELE gene could be a risky genotype for type 2 diabetes mellitus in the Iraqi population." (PMID 36617649, 2022).
Sepsis (63 papers, 2009 to 2025). Sepsis is defined as life-threatening organ dysfunction caused by a dysregulated host response to infection. "The anti-inflammatory function of GLP1-RAs was suggested to be through the inhibition of tumor necrosis factor alpha (TNFα) and decreases in vascular cell adhesion protein 1 (VCAM-1), intercellular adhesion molecules 1 (ICAM-1) and E-selectin expression in an animal sepsis model." (PMID 36932379, 2023). "Together, the data support that SIRT2 regulates microvascular inflammation: low SIRT2 increases and high SIRT2 decreases leukocyte/platelet adhesion in sepsis by controlling ICAM-1 and E-selectin expression." (PMID 28503576, 2017). "In the microvessels, on the other hand, increased E-selectin expression was accompanied by the recruitment of neutrophils, but not T lymphocytes, at the early stage after CLP-induced sepsis initiation." (PMID 39200137, 2024).
breast carcinoma (53 papers, 2007 to 2025). "Triculture tumor spheroids comprised of E-selectin expressing endothelial cells, normal human lung fibroblasts and human breast cancer cell line have been used to study an E-selectin drug delivery system for targeting tumor vasculature." (PMID 38254117, 2024). "Metastatic cells are able to repurpose this E-selectin binding as a means to promote metastasis; in mouse models, metastatic breast cancer cells were shown to undergo MET upon binding with E-selectin expressed on the vascular endothelium." (PMID 32829692, 2020). "A short while later, the same authors developed an ESTA-based approach to block E-selectin-supported hematogenous metastases of ER−/CD44+ breast cancer cells by preventing their adhesion to E-selectin-expressing premetastatic endothelial niche." (PMID 30428522, 2018). "Additional evidence for a specific interaction of breast cancer cells with P-selectin came from control experiments in which parental or E-selectin-expressing CHO cells were used." (PMID 30400820, 2018). "At a hematogenous wall shear rate, ZR-75-1 breast cancer cells specifically adhered to E-selectin expressing human umbilical vein endothelial cells when tested in parallel plate flow chamber adhesion assays." (PMID 22970241, 2012). "Both P- and E-selectin expression was significantly elevated on endothelial cells of breast cancer patients." (PMID 24957768, 2012). "The consistent high E-selectin expression level in the bone micro-vessels might be the reason for the high incidents of breast cancer bone metastasis." (PMID 33777909, 2021). "Additionally, E-selectin antagonists were also shown to prevent hematogenous metastasis of breast cancer via the inhibition of a shear-resistant adhesion of cancer cells to E-selectin-expressing blood vessels on the PMN." (PMID 35006432, 2021). "Therefore, we tested ESTA-1 binding to E-selectin expressing vessels in both human carcinoma pathology samples and 4T1 breast cancer xenograft animal model." (PMID 20927342, 2010). "Cell surface labeling with the E-selectin extracellular domain/Fc chimera (exE-selectin/Fc) showed that the transmigration capacity of breast cancer cells was correlated to both the expression level and localization pattern of E-selectin binding protein(s) on the tumor cell surface." (PMID 18350162, 2008). "Since the migration results suggest that E-selectin plays a critical role in mediating breast cancer cell transendothelial migration, we next examined the interactions of breast cancer cells with a soluble recombinant protein of E-selectin extracellular domain (exE-selectin/Fc)." (PMID 18350162, 2008).
COVID-19 (48 papers, 2021 to 2025). A disease caused by infection with severe acute respiratory syndrome coronavirus 2. "In our research, SELE and CCL20 have been identified as potential diagnostic biomarkers for COVID-19 in conjunction with pulmonary hypertension (PH)." (PMID 38653779, 2024). "However, our Mendelian randomization analyses showed that higher BMI is causal for higher levels of the COVID-19 protective proteins SELE, KEL, SELL, and causal for lower levels of the COVID-19 risk increasing proteins C1GALT and RAB14." (PMID 35239653, 2022). "In this study, because of the significance of SELE and CCL20 in the pathogenesis of COVID-19 and PH, we chose them as drug prediction and molecular docking targets." (PMID 38653779, 2024). "There was a statistically significant difference in the expression of SELE and CCL20 between the pulmonary hypertension and control groups and between COVID-19 and control groups." (PMID 38653779, 2024). "Moreover, cell adhesion markers such as ICAM1, PECAM1, and SELE were markedly, and significantly, upregulated in COVID-19, influenza, and non-influenza viral myocarditis (FDR < 0.001)." (PMID 36371548, 2023).
Stroke (46 papers, 2010 to 2026). Sudden impairment of blood flow to a part of the brain due to occlusion or rupture of an artery to the brain. "In the murine stroke model, upregulation of E-selectin expression was observed in the ischemic cerebral vasculature after reperfusion and persisted for 24 h." (PMID 37509028, 2023). "Stroke patients with unfavorable outcomes had a lower proportion of small-sized HDLs and increased plasma levels of E-selectin (SELE) and the intercellular adhesion molecule 1 (ICAM1)." (PMID 32708891, 2020).